RPS11 (ribosomal protein S11)
Description:
Component of the small ribosomal subunit. The ribosome is a large ribonucleoprotein complex responsible for the synthesis of proteins in the cell. Part of the small subunit (SSU) processome, first precursor of the small eukaryotic ribosomal subunit. During the assembly of the SSU processome in the nucleolus, many ribosome biogenesis factors, an RNA chaperone and ribosomal proteins associate with the nascent pre-rRNA and work in concert to generate RNA folding, modifications, rearrangements and cleavage as well as targeted degradation of pre-ribosomal RNA by the RNA exosome.
Synonyms: S11; uS17
Tractability: Small molecule: an approved drug acts on it; a structure with a bound ligand is known; a high-quality ligand is known. PROTAC: ubiquitination databases record sites on it; its protein half-life has been measured; a small molecule that binds it is known. Other modalities: a drug acting on it is in phase 2 or 3 trials.
Target class: Other cytosolic protein
Gene: Protein-coding gene on chromosome 19 (49,496,365 to 49,499,708, forward strand). Ensembl gene ENSG00000142534.
Subcellular location: Cytoplasm; Nucleus, nucleolus
Subcellular location (Human Protein Atlas): Cytosol; Endoplasmic reticulum; Nucleoli
Pathways (Reactome):
Metabolism of proteins: Eukaryotic Translation Termination; Formation of a pool of free 40S subunits; Formation of the ternary complex, and subsequently, the 43S complex; GTP hydrolysis and joining of the 60S ribosomal subunit; L13a-mediated translational silencing of Ceruloplasmin expression; PELO:HBS1L and ABCE1 dissociate a ribosome on a non-stop mRNA; Peptide chain elongation; Ribosomal scanning and start codon recognition; SRP-dependent cotranslational protein targeting to membrane; Translation initiation complex formation; ZNF598 and the Ribosome-associated Quality Trigger (RQT) complex dissociate a ribosome stalled on a no-go mRNA
Disease: SARS-CoV-1 modulates host translation machinery; SARS-CoV-2 modulates host translation machinery; Viral mRNA Translation
Metabolism of RNA: Major pathway of rRNA processing in the nucleolus and cytosol; Nonsense Mediated Decay (NMD) enhanced by the Exon Junction Complex (EJC); Nonsense Mediated Decay (NMD) independent of the Exon Junction Complex (EJC)
Cellular responses to stimuli: Response of EIF2AK4 (GCN2) to amino acid deficiency
Developmental Biology: Regulation of expression of SLITs and ROBOs
Metabolism: Selenocysteine synthesis
Gene Ontology:
Molecular function: protein binding; RNA binding; structural constituent of ribosome
Biological process: ribosomal small subunit biogenesis; cytoplasmic translation; translation
Cellular component: cytoplasm; cytosolic ribosome; cytosolic small ribosomal subunit; extracellular exosome; focal adhesion; membrane; nucleolus; small-subunit processome; cytosol; nucleoplasm; ribosome; synapse
Genetic constraint (gnomAD): Loss-of-function variants: 0 observed, 20.65 expected, observed/expected ratio (o/e) 0, 90% interval 0 to 0.14. The synonymous counts are far from expectation, so gnomAD's model fits this gene poorly and the ratio says little. Missense variants: 127 observed, 222.9 expected, observed/expected ratio (o/e) 0.57, 90% interval 0.49 to 0.66. Synonymous variants: 107 observed, 78.56 expected, observed/expected ratio (o/e) 1.36, 90% interval 1.16 to 1.6.
Homologues: Orthologues: chimpanzee RPS11 (100% identical), dog RPS11 (100% identical), guinea pig RPS11 (100% identical), macaque RPS11 (100% identical), mouse Rps11 (100% identical), pig RPS11 (100% identical), rabbit RPS11 (100% identical), tropical clawed frog rps11 (94% identical), zebrafish rps11 (92% identical), zebrafish rps11l (80% identical), rat Rps11l1 (77% identical), Drosophila melanogaster RpS11 (69% identical), and 1 more.
Diseases named in the same sentence as RPS11 in open-access papers:
RPS11 is named in the same sentence as 30 diseases in open-access papers, as found by Europe PMC text mining. Sharing a sentence is not in itself a finding about the gene and the disease. The quoted sentences say what the papers report.
glioblastoma (9 papers, 2015 to 2023). The most malignant astrocytic tumor (WHO grade IV). "Elevated levels of RPS11 have been found to be associated with a poor prognosis in patients with glioblastoma." (PMID 36733371, 2022). "In humans RPS11 phosphorylation is linked to Parkinson's disease and higher levels of RPS11 correlate with poorer prognosis in glioblastoma patients." (PMID 34283226, 2022). "From the analysis conducted in this study, it is clear that most of the genes associated with glioblastoma prognosis are ribosomal protein genes, represented by RPS10 and RPS11." (PMID 36733371, 2022). "Eight genes associated with glioblastoma prognosis were identified based on LASSO analysis: RPS10, RPS11, RPS19, RSL24D1, RPL39L, EIF3E, NUDT5, and RPF1." (PMID 36733371, 2022). "In glioblastoma, increased expression of uS17/RPS11 and uS10/RPS20 enhanced stress-resistant CSC phenotypes." (PMID 34627375, 2021). "For example, with glioblastoma, eS6 (RPS6), eS27 (RPS27), uS8 (RPS15A) and eL34 (RPL34) are known as oncogenic, whereas uL18 (RPL5), uS17 (RPS11), uS9 (RPS16) and uS13 (RPS18) are found to have a tumor-suppressive function." (PMID 37511213, 2023). "Eight genes—RPS10, RPS11, RPS19, RSL24D1, RPL39L, EIF3E, NUDT5, and RPF—were found to have an expression in the prognosis of glioblastoma." (PMID 36733371, 2022). "RPS11 and RPS20 have been proposed as prognostic markers in glioblastoma and the down-regulation of RPL10 correlates with altered treatment response to dimethylaminoparthenolide (DMAPT) in pancreatic cancer." (PMID 29530001, 2018). "Moreover, increased expression of ribosomal proteins RPS11 and RPS20 predicts shorter survival in glioblastoma patients." (PMID 35281852, 2022).
breast carcinoma (2 papers, 2009 to 2015). "Moreover, RPS11 was shown to be specifically downregulated in apoptotic breast carcinoma cells." (PMID 26506620, 2015). "Two new control genes for breast cancer – UBB and RPS11 – have been identified and validated by RT-QPCR." (PMID 19187545, 2009).
glioma (2 papers, 2022). A benign or malignant brain and spinal cord tumor that arises from glial cells (astrocytes, oligodendrocytes, ependymal cells). "The expression of RPS11 was confirmed to be associated with susceptibility to TOP2 poisons across multiple cancer cell lines, including glioma cells." (PMID 35841000, 2022). "Only RPS11 and RPL36A were previously found to be beneficial in glioma as prognostic predictors." (PMID 36497269, 2022).
acute myocardial infarction (1 paper, 2025). Necrosis of the myocardium, as a result of interruption of the blood supply to the area. "In our research, involving bioinformatics analyzing, clinical studying, and many experimental validations, we paid an attention to mitophagy and we presented the importance of RPS11 in the event of acute myocardial infarction (AMI) and its transition to ischemic cardiomyopathy (ICM)." (PMID 40114920, 2025).
Alzheimer disease (1 paper, 2024). A progressive, neurodegenerative disease characterized by loss of function and death of nerve cells in several areas of the brain leading to loss of cognitive function such as memory and language. "The down-regulated DEGs in DM versus NN were primarily focused on ribosome (approximately 80 DEGs, including RPL37 and RPS11), Alzheimer’s disease (about 86 DEGs), and cardiac muscle contraction (about 22 DEGs, such as UQCRQ and TNNC1)." (PMID 38660519, 2024). "The DEGs that were down-regulated in DM compared to NM were primarily related to the ribosome (about 23 DEGs, including RPL37A and RPS11), Alzheimer’s disease (about 19 DEGs, including APC2 and COX8A), and non-alcoholic fatty liver disease (about 11 DEGs, such as SNCA and COX8A)." (PMID 38660519, 2024).
colorectal carcinoma (1 paper, 2015). A malignant epithelial neoplasm that arises from the colon or rectum and invades through the muscularis mucosa into the submucosa. "The expression of RPS11 protein was barely detected in normal colon mucosa but was upregulated in immature mucosal epithelium located in the crypt base and in colorectal carcinoma cells." (PMID 26506620, 2015).
COVID-19 (1 paper, 2025). A disease caused by infection with severe acute respiratory syndrome coronavirus 2. "In COVID-19, these included RPL13A, RPL6, RPL13, RPLP2, RPS11, UBA52, and the ribosomal pseudogene RPL13AP20." (PMID 41020849, 2025).
hepatocellular carcinoma (1 paper, 2024). A malignant tumor that arises from hepatocytes. "In hepatocellular carcinoma (HCC) tumors, high RPS11 levels were associated with shorter overall survival (OS) and recurrence-free survival (RFS) of HCC patients after curative resection." (PMID 38397997, 2024).
medulloblastoma (1 paper, 2015). A malignant, invasive embryonal neoplasm arising from the cerebellum.
osteosarcoma (1 paper, 2023). A usually aggressive malignant bone-forming mesenchymal neoplasm, predominantly affecting adolescents and young adults. "In response to stress, uS3/RPS3, uS4/RPS9, uS17/RPS11, eS24/RPS24, eL6/RPL6, uL13/RPL13A, eL14/RPL14, eL30/RPL30, eL42L/RPL36AL, and RACK1 in U2OS (human osteosarcoma) cells have O-linked β-N-acetylglucosamine (O-GlcNAc) modifications." (PMID 37047306, 2023).
ulcerative colitis (1 paper, 2023). An inflammatory bowel disease involving the mucosal surface of the large intestine and rectum. "Furthermore, we observed that the upregulation of MYH11 inhibited tumor growth in GC45, and genes encoding ribosomal proteins (RPL16, RPS11, and RPS21) were related to ulcerative colitis and GC." (PMID 37488424, 2023).
viral infection (1 paper, 2017). "Given that 30S ribosomal protein is a key to protein synthesis, investigating the interaction between endogenous RPS11 and viral protein can elucidate the effect of host protein on viral infection." (PMID 28806733, 2017). "Additionally, the knockdown of RPS11 effect on viral infection was not a consequence of a general reduction in protein synthesis but was because of the specificity of CMVLS2b expression." (PMID 28806733, 2017).
tumor (12 papers, 2015 to 2025). "RPS11 encodes the RPS11 protein, which is overexpressed in various malignancies and is associated with tumor recurrence." (PMID 36733371, 2022). "Conversely, the enrichment of RPL5 and RPS11 in T/NK cells indicates that lactylation may influence lymphocyte function and thus modulate the anti-tumor immune response." (PMID 40740857, 2025). "The RPS11 protein is overexpressed in diverse malignancies and correlates with tumor recurrence." (PMID 38397997, 2024). "When overexpressed, RPS11 and RPS20 were generally diffusely upregulated in the tumor cell population." (PMID 26506620, 2015). "Moreover, prognostic significance of RPS11 was shown in newly diagnosed GBM but not in recurrent tumors, suggesting that RPS11 upregulation is of benefit to GBM tumor cells at initial treatment when radiochemotherapy is given to essentially all newly diagnosed GBM patients." (PMID 26506620, 2015).
infection (5 papers, 2017 to 2025). The state of being infected such as from the introduction of a foreign agent such as serum, vaccine, antigenic substance or organism. "On day 8 after infection, the expression levels of RPS11 and RPS20 were upregulated to varying degrees." (PMID 35313969, 2022). "The silencing of SNORA/Ds encoded within RPS11 (SNORD35B), SNHG3 (SNORA73A, SNORA73B), and SNHG1 (SNORD22, SNORD25, SNORD26, SNORD27, SNORD28, SNORD29, SNORD30, SNORD31) inhibited infection with influenza A virus." (PMID 36430145, 2022). "In this paper, the endogenous protein RPS11 influenced the exogenous infection." (PMID 28806733, 2017). "Thus, exogenous infection was influenced by the endogenous protein RPS11." (PMID 28806733, 2017). "On the contrary, MOPV infection led to the late (48 h) release of PSMD2, RPS11, HNRNPA3, ATP1A1, TARS1, and PRKAR1A, whereas significantly elevated levels of IGFBP3 were found at both timepoints." (PMID 35337059, 2022).
cardiac diseases (1 paper, 2025). "While RPS11 has not been previously reported in cardiac diseases, other ribosomal proteins(RPS6) have been associated with cardiac conditions." (PMID 40114920, 2025).
cardiovascular disease (1 paper, 2007). "Moreover some ribosomal proteins were highly induced (up to 119,98 fold change in expression for RPS11) as already observed in HUVECs treated with asymmetrical dimethylarginine (ADMA), an endogenous inhibitor of nitric oxide synthase considered a risk factor for cardiovascular disease." (PMID 17534423, 2007).
RPS11 also shares sentences with these, for which no sentence is quoted: cancer (4 papers); prostate carcinoma (2); Autoimmunity (1); ischemic cardiomyopathy (1); leukemia (1); liver cancer (1); lymphoma (1); macrosomia (1); myocardial infarction (1); non-alcoholic fatty liver disease (1); pancreatic cancer (1); Parkinson disease (1); renal carcinoma (1); squamous cell lung carcinoma (1).